NTRK2 (neurotrophic receptor tyrosine kinase 2)
Description:
Receptor tyrosine kinase involved in the development and the maturation of the central and the peripheral nervous systems through regulation of neuron survival, proliferation, migration, differentiation, and synapse formation and plasticity (By similarity). Receptor for BDNF/brain-derived neurotrophic factor and NTF4/neurotrophin-4. Alternatively can also bind NTF3/neurotrophin-3 which is less efficient in activating the receptor but regulates neuron survival through NTRK2. Upon ligand-binding, undergoes homodimerization, autophosphorylation and activation. Recruits, phosphorylates and/or activates several downstream effectors including SHC1, FRS2, SH2B1, SH2B2 and PLCG1 that regulate distinct overlapping signaling cascades. Through SHC1, FRS2, SH2B1, SH2B2 activates the GRB2-Ras-MAPK cascade that regulates for instance neuronal differentiation including neurite outgrowth. Through the same effectors controls the Ras-PI3 kinase-AKT1 signaling cascade that mainly regulates growth and survival. Through PLCG1 and the downstream protein kinase C-regulated pathways controls synaptic plasticity. Thereby, plays a role in learning and memory by regulating both short term synaptic function and long-term potentiation. PLCG1 also leads to NF-Kappa-B activation and the transcription of genes involved in cell survival. Hence, it is able to suppress anoikis, the apoptosis resulting from loss of cell-matrix interactions. May also play a role in neutrophin-dependent calcium signaling in glial cells and mediate communication between neurons and glia.
Synonyms: Trk-B; TRKB; DEE58; EIEE58; GP145-TrkB; OBHD
Tractability: Small molecule: an approved drug acts on it; a structure with a bound ligand is known; a high-quality ligand is known; it belongs to a druggable protein family. Antibody: UniProt places it where antibodies can reach, with high confidence; its Gene Ontology location is reachable by antibodies, with high confidence; UniProt predicts a signal peptide or a membrane-spanning region; the Human Protein Atlas places it where antibodies can reach. PROTAC: it is named in the literature on targeted protein degradation; UniProt records ubiquitination sites on it; its protein half-life has been measured; a small molecule that binds it is known. Other modalities: an approved drug acts on it.
Target class: Protein Kinase; Tyrosine protein kinase Trk family; TK protein kinase group; Enzyme; Kinase
Chemical probes: AZD1332 (high quality), D2202-1 (high quality), GNF-5837 (high quality), larotrectinib (high quality)
Safety:
Unwanted effects reported when the protein is acted on. In parentheses: how it was acted on, where the effect was seen, and who reports it.
suicidal thoughts (source: ClinPGx)
Gene: Protein-coding gene on chromosome 9 (84,668,375 to 85,095,751, forward strand). Ensembl gene ENSG00000148053.
Subcellular location: Cell membrane; Endosome membrane; Early endosome membrane; Cell projection, axon; Cell projection, dendrite; Cytoplasm, perinuclear region; Postsynaptic density
Subcellular location (Human Protein Atlas): Plasma membrane; Primary cilium tip; Vesicles
Pathways (Reactome):
Signal Transduction: Activated NTRK2 signals through CDK5; Activated NTRK2 signals through FRS2 and FRS3; Activated NTRK2 signals through FYN; Activated NTRK2 signals through PI3K; Activated NTRK2 signals through PLCG1; Activated NTRK2 signals through RAS; BDNF activates NTRK2 (TRKB) signaling; NGF-independant TRKA activation; NTF3 activates NTRK2 (TRKB) signaling; NTF4 activates NTRK2 (TRKB) signaling; NTRK2 activates RAC1; PI5P, PP2A and IER3 Regulate PI3K/AKT Signaling; PIP3 activates AKT signaling
Disease: Constitutive Signaling by Aberrant PI3K in Cancer
Gene Ontology:
Molecular function: brain-derived neurotrophic factor receptor activity; neurotrophin binding; protease binding; protein binding; protein tyrosine kinase activity; brain-derived neurotrophic factor binding; protein homodimerization activity; ATP binding; neurotrophin receptor activity; protein kinase activity; transmembrane receptor protein tyrosine kinase activity
Biological process: brain-derived neurotrophic factor receptor signaling pathway; negative regulation of amyloid-beta formation; cell surface receptor protein tyrosine kinase signaling pathway; cellular response to brain-derived neurotrophic factor stimulus; central nervous system neuron development; cerebral cortex development; learning; negative regulation of neuron apoptotic process; neuron differentiation; neuron migration; positive regulation of axonogenesis; positive regulation of cell population proliferation; positive regulation of gene expression; positive regulation of MAPK cascade; positive regulation of neuron projection development; positive regulation of phosphatidylinositol 3-kinase/protein kinase B signal transduction; protein autophosphorylation; regulation of GTPase activity; circadian rhythm; long-term synaptic potentiation; negative regulation of anoikis; neurotrophin signaling pathway; oligodendrocyte differentiation; peripheral nervous system neuron development; regulation of phosphatidylinositol 3-kinase/protein kinase B signal transduction; and 1 more
Cellular component: plasma membrane; receptor complex; axon; axon terminus; dendrite; dendritic spine; early endosome; early endosome membrane; endosome membrane; perinuclear region of cytoplasm; postsynaptic density; cytosol; endosome; membrane; terminal bouton
Genetic constraint (gnomAD): Loss-of-function variants: 5 observed, 85.49 expected, observed/expected ratio (o/e) 0.0585, 90% interval 0.03 to 0.12. The upper end of that interval is the gene's LOEUF score, 0.12, which puts it in group 1 of 6, group 1 being the genes least tolerant of losing a copy. Missense variants: 603 observed, 1,079.2 expected, observed/expected ratio (o/e) 0.56, 90% interval 0.52 to 0.6. Synonymous variants: 361 observed, 415.23 expected, observed/expected ratio (o/e) 0.87, 90% interval 0.8 to 0.95.
Cancer hallmarks: invasion and metastasis (promotes); angiogenesis (promotes); proliferative signalling (promotes); genome instability and mutations (promotes); escaping programmed cell death (promotes); genome instability and mutations (suppresses)
Homologues: Orthologues: chimpanzee NTRK2 (100% identical), macaque NTRK2 (99% identical), dog NTRK2 (98% identical), pig NTRK2 (97% identical), rabbit NTRK2 (95% identical), rat Ntrk2 (93% identical), guinea pig NTRK2 (92% identical), mouse Ntrk2 (92% identical), tropical clawed frog ntrk2 (70% identical), zebrafish ntrk2a (61% identical), zebrafish ntrk2b (59% identical). Paralogues in human: NTRK3 (53% identical), NTRK1 (47% identical), MUSK (25% identical), ROS1 (25% identical), ROR1 (25% identical), ROR2 (24% identical), IGF1R (24% identical), INSR (24% identical), INSRR (24% identical), MET (20% identical), FLT4 (20% identical), DDR1 (20% identical), and 41 more.
Diseases named in the same sentence as NTRK2 in open-access papers:
NTRK2 is named in the same sentence as 416 diseases in open-access papers, as found by Europe PMC text mining. Sharing a sentence is not in itself a finding about the gene and the disease. The quoted sentences say what the papers report.
depression (350 papers, 2008 to 2026). "On the other hand, the CC genotype of the rs2289656 polymorphism in the NTRK2 gene was associated with an increased risk of suicide behavior in patients with depression." (PMID 40869374, 2025). "Genotype-dependent differences in NTRK2 have been observed in white matter properties among patients with depression and have been linked to emotional arousal in healthy individuals." (PMID 38561734, 2024). "While NTRK2 is essential for normal neurological processes, its dysregulation has been implicated in neuropsychiatric disorders (depression, anxiety, and schizophrenia), synaptic plasticity, neurotransmitter release, and tumour growth and progression." (PMID 38255751, 2024). "Accumulating evidence suggest a relationship between NTRK2 and a broad range of psychiatric disorders, especially those associated with stress, including depression, schizophrenia, and anxiety disorders." (PMID 38561734, 2024). "Concerning the human NTRK2 gene that encodes trkB, it has been reported that one polymorphism in that gene was associated with major depression and the rate of suicidal attempts." (PMID 39194496, 2024). "The NTRK2 gene has been reported to be associated with several psychiatric diseases, such as depression and bipolar disorder, and it has also been reported to be influenced by environmental factors such as stress." (PMID 32149119, 2020). "BDNF/NTRK2 signaling has been linked to both the pathophysiology of depression and the mode of action of antidepressants." (PMID 30765816, 2019). "This study aimed to test for association between antidepressant-worsening suicidal ideation and polymorphisms of BDNF/NTRK2 neurotrophin pathway genes, known to be involved in depression and suicide." (PMID 27378793, 2016). "The list includes several genes previously implicated in depression including the NTRK2, AXL and TAC1 genes." (PMID 25734512, 2015). "In conclusion, our results indicate that common, functionally significant polymorphisms in BDNF and NTRK2 partially modulate stress-coping strategies, depression, and anxiety." (PMID 26445699, 2015). "Gender-specific effects have been reported for BDNF associations with depression and antidepressant treatment, as well as for NTRK2 with obsessive-compulsive disorder." (PMID 23750220, 2013). "In conclusion, the dysregulated expression of Ntrk2 played a contributory role in depression and the targeting of novel antidepressants." (PMID 37175269, 2023). "Overall, our study verified that during states of excessive oxidative stress, the PIK3CA/AKT1/NFE2L2/KEAP1 and PIK3CA/AKT1/BDNF/NTRK2 signaling pathways are suppressed, which induced OB rats to exhibit phenotypic behaviors of depression." (PMID 33935736, 2021). "Decreased expression of NTRK2 was repeatedly reported in postmortem brains of patients with psychiatric disorders and animal models of depression." (PMID 33875800, 2021). "Remarkably, healthy astrocytes treated with chronic cortisol dysregulated genes previously linked with depression including MAOA, which modulates neurotransmitter levels, and neurotrophin signaling gene NTRK2/TrkB." (PMID 34848679, 2021). "A particular SNP in the neurotrophic tyrosine kinase receptor type 2 (NTRK2 gene, encoding the receptor complex formed by TrkB) might contribute to comorbid HIV infection and major depressive disorder (MDD) in individuals with different ethnic backgrounds." (PMID 38138916, 2023). "Further investigation on the interaction between BDNF/NTRK2 and dopamine signaling in the brain is crucial for understanding not only the effect of stress on depression, but also for addictive behavior in the functional reorganization of neuronal networks in addiction and psychiatric disorders." (PMID 30765816, 2019).
depression (continued). "The neuroplastic pathway, including CREB, BDNF and its receptor (neurotrophic tyrosine kinase receptor, type 2 [NTRK2]), has a key role to play in the adaptation of the brain to stress, with the variations of these genes highlighted as potential depression risk factors." (PMID 31406011, 2019). "Neurotrophic tyrosine kinase receptor type 2 (NTRK2) and ligand brain-derived neurotrophic factor (BDNF) are the subject of intense investigation in psychiatry and have been associated with anxiety, suicide, and depression, amongst other disorders." (PMID 22802923, 2012). "Among the different pathways involved in depression and suicidal behavior, the neurotrophin pathway, also known as BDNF/NTRK2 pathway, is a major one to consider." (PMID 27378793, 2016). "Moreover, the binding of NTRK2 and BDNF activates the PIK3CA/AKT1 pathway, which promotes synaptic plasticity and enhances long-term potentiation to alleviate depression." (PMID 33935736, 2021). "After LBRD standard decoction administration, four differentially expressed miRNAs, rno-miR-144-3p, rno-miR-495, rno-miR-34c-5p, and rno-miR-24-3p, and six differentially expressed mRNAs, Calml4, Ntrk2, VGAT, Gad1, Nr1d1, and Bdnf overlapped in the in vivo/vitro depression model." (PMID 34674715, 2021). "Although several studies have examined the relationships between depression and BDNF or NTRK2, few have examined whether these genes contribute to an individual’s stress-coping style." (PMID 26445699, 2015). "Thus, several studies have examined the relationship between depression and BDNF and NTRK2, although few have examined how these genes contribute to an individual’s vulnerability to stress." (PMID 26445699, 2015). "In line with the neurotrophic hypothesis of depression, genes coding for members of the neurotrophic tyrosine receptor kinase family such as Ntrk2 and Ntrk3 were normalized by FLX action in a reverse direction compared to observation in rodent stress models of depression." (PMID 36362329, 2022).
neuroblastoma (126 papers, 2007 to 2026). Neuroblastoma (NB) is the most common solid, extracranial childhood tumor. "NTRK2 has been implicated in several types of cancers, including neuroblastoma, medulloblastoma, Wilm’s tumor, and adenocarcinomas of the lung, prostate, and pancreas as well as multiple myeloma." (PMID 34249950, 2021). "While high NTRK2 expression combined with amplified MYCN is a marker for high-risk neuroblastoma, NTRK2 pathway activation by BDNF ligand treatment is also known to aid RA-mediated differentiation." (PMID 28187790, 2017). "Specifically, TrkA (NTRK1) and C (NTRK3) expression are associated with favorable outcomes in neuroblastoma, while TrkB (NTRK2) is associated with biologically aggressive disease." (PMID 29207623, 2017). "NTRK2 has previously been implicated in several types of cancers including neuroblastoma, medulloblastoma, Wilm’s tumor and adenocarcinomas of the lung, prostate and pancreas as well as multiple myeloma." (PMID 27672444, 2016). "In contrast, NTRK2 expression in neuroblastoma has been reported to be associated with MYCN amplification, enhanced migratory properties leading to early metastases and a resistance to first-line chemotherapeutics, all of which contribute to poor patient survival." (PMID 32296437, 2020). "Next, we tested the expression of NTRK2 (neurotrophic receptor tyrosine kinase 2, TrkB) and BCL2 (B cell CLL/lymphoma 2); both genes linked to neural differentiation whose expression is increased in RA-treated neuroblastoma cells." (PMID 35831557, 2022). "Expression of the NTRK2 gene, one of the mainmarkers of neuroblastoma cell differentiation, was significantly upregulated inSH-SY5Y cells exposed to retinoic acid.We found similar changes inNTRK2 expression in TE-671 cells treated with SCH772984." (PMID 35127149, 2021). "NTRK1-expressing neuroblastoma cells were most susceptible to both CD4+ and CD8+ CAR T cell-mediated killing, while NTRK2-expressing cells were significantly more resistant." (PMID 32296437, 2020). "The direct relationship between ATRA treatment and NTRK2 gene expression in neuroblastoma was supported by TSS analysis in our study." (PMID 32149119, 2020). "In the current study, both the agonist and the antagonist of the RAR caused an increase of TrkB in SH-SY5Y-A cells, which confirms that the expression of the NTRK2 gene is directly controlled by ATRA via the RAR in neuroblastoma cells." (PMID 32149119, 2020). "Even though NTRK1 and NTRK2 share extensive sequence similarity and similar proximal signaling targets, their expression is correlated with divergent effects on neuroblastoma biology and malignancy." (PMID 32296437, 2020). "Ntrk2 is also targeted, less selectively by other RTKi’s in the clinic or in early stage clinical development e.g. Lestaurtinib (for neuroblastoma;) and PLX7486 (pancreatic adenocarcinoma; ClinicalTrials.gov identifier: NCT01804530)." (PMID 25710496, 2015). "NTRK2 has been found frequently overexpressed in human cancers, including pancreatic and prostate carcinoma, Wilms’ tumor and neuroblastomas, particularly those with aggressive behavior and poor prognosis." (PMID 25629528, 2015). "Reanalysis of microarray data from human SY5Y neuroblastoma cells stably transfected with either NTRK1 or NTRK2 revealed upregulation of the mRNA for the SC growth factor, NRG1, in NTRK1-positive cells." (PMID 25361003, 2014). "GGA, similar to ATRA, has been confirmed to induce a significant increase in the expression of neurotrophic receptor kinase 2 (NTRK2 or TrkB) and RARβ protein in human neuroblastoma cell line SH-SY5Y, indicating that GGA possesses a “retinoid effect” like ATRA." (PMID 38786033, 2024). "Furthermore, mutually exclusive expression of the neurotrophic receptor tyrosine kinases 1 or 2 (NTRK1, NTRK2) has prognostic significance, and both kinases contribute to distinct neuroblastoma biologies, in particular to differences in tumor immunogenicity." (PMID 32296437, 2020).